POMC (proopiomelanocortin)
Description:
Precursor protein of pituitary hormones that are involved in diverse physiological processes, including the regulation of energy balance, stress response, immune function and skin pigmentation. [Corticotropin]: Functions as a ligand for the melanocortin receptors MC1R, MC2R, MC3R and MC5R. Activation of MC1R increases melanogenesis in melanocytes found in the skin and hair. Binding to MC2R stimulates the adrenal glands to secrete cortisol. Contributes to the regulation of energy homeostasis through activation of MC3R (Probable). Involved in the regulation exocrine gland function through MC5R activation (By similarity). [Melanocyte-stimulating hormone alpha]: Serves as a ligand for the melanocortin receptors MC1R, MC3R, MC4R and MC5R. Activation of MC1R promotes melanogenesis in melanocytes of the skin and hair. Contributes to the regulation of energy homeostasis through activation of MC3R (Probable). Through MC4R activation, functions as an anorexigenic peptide. Promotes immunosuppression and involved in the regulation exocrine gland function through MC5R activation (By similarity). [Melanocyte-stimulating hormone beta]: Functions as a ligand for the melanocortin receptors MC1R, MC3R, MC4R and MC5R. Activation of MC1R increases melanogenesis in melanocytes found in the skin and hair (Probable). Contributes to the regulation of energy homeostasis through activation of MC3R (Probable). Through MC4R activation, functions as an anorexigenic peptide. Involved in the regulation exocrine gland function through MC5R activation (By similarity). [Melanotropin gamma]: Functions as a ligand for the melanocortin receptors MC1R, MC3R, MC4R and MC5R. Activation of MC1R increases melanogenesis in melanocytes found in the skin and hair (Probable). Contributes to the regulation of energy homeostasis through activation of MC3R (Probable). Binds to MC4R with low potency. Involved in the regulation exocrine gland function through MC5R activation (By similarity). [Beta-endorphin]: Endogenous orexigenic opiate. [Met-enkephalin]: Endogenous opiate.
Synonyms: ACTH; CLIP; MSH; POC; NPP; LPH; OBAIRH
Tractability: Small molecule: a structure with a bound ligand is known. Antibody: its Gene Ontology location is reachable by antibodies, with high confidence; UniProt places it where antibodies can reach, with medium confidence; UniProt predicts a signal peptide or a membrane-spanning region.
Gene: Protein-coding gene on chromosome 2 (25,160,853 to 25,168,903, reverse strand). Ensembl gene ENSG00000115138.
Subcellular location: Secreted
Pathways (Reactome):
Signal Transduction: G alpha (i) signalling events; G alpha (s) signalling events; G-protein activation; Opioid Signalling; Peptide ligand-binding receptors
Metabolism: Androgen biosynthesis; Endogenous sterols; Glucocorticoid biosynthesis
Developmental Biology: Transcriptional and post-translational regulation of MITF-M expression and activity
Disease: Defective ACTH causes obesity and POMCD
Gene expression (Transcription): FOXO-mediated transcription of oxidative stress, metabolic and neuronal genes
Immune System: Interleukin-4 and Interleukin-13 signaling
Metabolism of proteins: Peptide hormone biosynthesis
Gene Ontology:
Molecular function: G protein-coupled receptor binding; hormone activity; protein binding; signaling receptor binding; type 1 melanocortin receptor binding; type 3 melanocortin receptor binding; type 4 melanocortin receptor binding
Biological process: cell-cell signaling; cellular pigmentation; generation of precursor metabolites and energy; negative regulation of tumor necrosis factor production; positive regulation of transcription by RNA polymerase II; regulation of appetite; signal transduction; calcium-mediated signaling; positive regulation of adenylate cyclase-activating G protein-coupled receptor signaling pathway; regulation of blood pressure; response to melanocyte-stimulating hormone; positive regulation of oxytocin production
Cellular component: extracellular region; cytoplasm; secretory granule; secretory granule lumen
Genetic constraint (gnomAD): Loss-of-function variants: 23 observed, 17.63 expected, observed/expected ratio (o/e) 1.3, 90% interval 0.94 to 1.8. The upper end of that interval is the gene's LOEUF score, 1.8, which puts it in group 6 of 6, group 1 being the genes least tolerant of losing a copy. Missense variants: 451 observed, 366.66 expected, observed/expected ratio (o/e) 1.23, 90% interval 1.14 to 1.33. Synonymous variants: 179 observed, 161 expected, observed/expected ratio (o/e) 1.11, 90% interval 0.98 to 1.26.
Homologues: Orthologues: chimpanzee POMC (99% identical), dog POMC (81% identical), macaque POMC (77% identical), mouse Pomc (70% identical), rat Pomc (69% identical), guinea pig POMC (69% identical), tropical clawed frog pomc (54% identical), zebrafish pomca (37% identical), zebrafish pomcb (26% identical).
Diseases named in the same sentence as POMC in open-access papers:
POMC is named in the same sentence as 757 diseases in open-access papers, as found by Europe PMC text mining. Sharing a sentence is not in itself a finding about the gene and the disease. The quoted sentences say what the papers report.
Obesity (722 papers, 2006 to 2026). Accumulation of substantial excess body fat. "POMC deficiency mutations are often associated with obesity, non-alcoholic fatty liver disease, type 2 diabetes, and certain circulatory problems; in particular, the chronic activation of POMC neurons reduces blood pressure." (PMID 40001512, 2025). "Implementing next-generation sequencing (NGS) to identify variants in Lep, LepR, MC4R, and POMC genes enables timely, genetically guided interventions for non-syndromic early-onset obesity in children and adolescents." (PMID 40278960, 2025). "Specific mutations in genes that participate in the leptin-melanocortin pathway, such as those encoding leptin, leptin receptor (LepR), melanocortin-4 receptor (MC4R), and pro-opiomelanocortin (POMC), are recognized to cause monogenic forms of obesity." (PMID 41321496, 2025). "Increasing data indicates that SNPs and rare mutations in genes such as FTO, MC4R, LEPR, and POMC influence not only the risk of obesity but also significantly impact weight loss, WR, and metabolic outcomes following bariatric surgery." (PMID 41226372, 2025). "Setmelanotide (Imcivree®) was approved in 2020 for obesity due to proopiomelanocortin (POMC), leptin receptor (LEPR), or PCSK1 deficiency, and later for Bardet–Biedl syndrome." (PMID 40843857, 2025). "It is indicated for patients aged ≥2 years with obesity due to proopiomelanocortin (POMC), PCSK1, leptin receptor (LEPR) deficiencies, or Bardet-Biedl syndrome (BBS), with dosing adjusted by age and weight." (PMID 41393538, 2025). "Another study showed that rapamycin alleviates age-dependent obesity, which is associated with increased mTOR signaling in hypothalamic POMC neurons." (PMID 40299431, 2025). "For example, while mutations in POMC are relatively rare (approximately 1 in 10,000), clinical cases of obesity have been associated with genetic aberrations of this hypothalamic neuropeptide." (PMID 40283207, 2025). "Dysfunction of POMC neurons or the MC4R leads to severe obesity and associated metabolic comorbidities." (PMID 40541585, 2025). "Investigating the regulation of the POMC gene by obesity-associated genes is a hotspot in obesity research." (PMID 40001512, 2025). "Clinical advancements include setmelanotide (IMCIVREETM, Rhythm Pharmaceuticals), an MC4R agonist approved for monogenic obesity disorders (POMC, LepR deficiencies)." (PMID 40278960, 2025). "In 2020, the FDA approved setmelanotide (Imcivree) for chronic weight management in patients with obesity due to POMC, PCSK1, or LEPR deficiency." (PMID 40636093, 2025). "This review highlights the recent findings on novel mutations of POMC, its derived obesity-related hormones, and their interactions with MCRs." (PMID 40001512, 2025). "Clinically, it is well known that a deficiency of POMC (bi-allelic variants) leads to hyperphagia, lower resting metabolic rate, and severe obesity with cutaneous pigmentation abnormalities (red hair and pale skin)." (PMID 40822950, 2025). "Genes implicated in monogenic obesity include POMC, LEP, LEPR, MC3R, and MC4R, while polygenic obesity involves variants in genes such as FTO, UCP1-3, MC4R, ADRB1-3, and SLC6A14." (PMID 41302083, 2025). "In the case of a loss‐of‐function mutation in the proopiomelanocortin (POMC) gene, humans become deficient in melanocortin peptides, leading to the display of red hair and suffering from obesity and adrenal insufficiency." (PMID 39910963, 2025). "In studies conducted in adults, SNPs in the genes FTO, MC4R, TMEM18, TNNI3K, SEC16B, GNPDA2, and POMC are strongly associated with obesity risk." (PMID 40722558, 2025). "For example, a strong association was observed between epigenetic variation and obesity risk, with data demonstrating increased DNA methylation of POMC in adolescents and adults with obesity." (PMID 40283207, 2025). "On the other hand, pro-opiomelanocortin (POMC) mutant C28F, implicated in early onset obesity, evades ERAD-mediated degradation and becomes aggregated instead." (PMID 40735229, 2025).
Obesity (continued). "Variants in three genes—ADCY3, GCK, and POMC—co-occurred with autosomal dominant mutations in key genes associated with both diabetes and obesity." (PMID 40149731, 2025). "This is also complicated by the fact that diet-induced obesity in mice results in leptin resistance, recently suggested to be caused by chronic mTOR activation in POMC neurons that reduces leptin signaling." (PMID 40702736, 2025). "Here we report that the SEL1L-HRD1 protein complex of the highly conserved ER-associated protein degradation (ERAD) machinery in POMC neurons is indispensable for leptin signaling in diet-induced obesity." (PMID 38260335, 2024). "This review provides a background on the genetic aetiologies for obesity and focuses on setmelanotide, its mechanism of action, and its efficacy as a treatment for obesity secondary to a number of genetic variants in the POMC/MC4R pathway." (PMID 39526054, 2024). "This endogenous and exogenous 4-HNE synergically causes POMC neuronal degeneration/death and obesity." (PMID 39683565, 2024). "POMC mutations: patients with complete loss of POMC gene function were diagnosed on the basis of secondary hypocortisolism, red hair, and extreme obesity." (PMID 38546831, 2024). "Given the involvement of these genes in crucial metabolic and behavioral pathways, investigating single nucleotide variants (SNVs) within FOXO3A, AMPK, and POMC can offer valuable insights into the molecular mechanisms driving obesity." (PMID 39484290, 2024). "Conversely, mice with inducible deletion of Azgp1 in POMC neurons exhibit the opposite metabolic phenotypes, showing increased susceptibility to diet-induced obesity." (PMID 38643150, 2024). "The mechanism involves a decrease in caloric intake and an increase in the expenditure of energy, ultimately contributing to the management of obesity in individuals with specific genetic conditions such as POMC, PCSK1, or LEPR deficiencies." (PMID 38540684, 2024). "In humans, homozygous POMC mutations cause clinical features involving deficiency of all its derivative peptides, including severe obesity, adrenal insufficiency, and red hair." (PMID 38019584, 2024). "It is specifically indicated for adult and pediatric patients aged 6 years and older with obesity caused by POMC, proprotein convertase subtilisin/kexin type 1 (PCSK1), or leptin receptor (LEPR) deficiency." (PMID 38540684, 2024). "Specifically, our results show that defects in the first-order neurons (e.g. POMC neurons) as the underlying cause of obesity in BBS." (PMID 38223458, 2024). "Children who have either homozygous or compound heterozygous mutations in the POMC gene provide the strongest evidence for a link between mutations in POMC and obesity." (PMID 39765543, 2024). "The role of these populations in leptin signalling has also been evaluated and, whereas a knockout of the LepR in AGRP/NPY neurons of adult mice causes extreme obesity, deletion of the LepR from adult POMC neurons has only a minimal effect." (PMID 39478220, 2024). "The other two are small molecules (glibenclamide to treat neonatal diabetes mellitus and setmelanotide to treat obesity associated with biallelic pro-opiomelanocortin (POMC), including PCSK1, deficiency obesity or leptin receptor (LEPR) deficiency obesity)." (PMID 38413985, 2024). "Genetic variations in SEMA3A have been reported to be associated with severe early onset obesity owing to disrupted SEMA3A signaling in pro-opiomelanocortin (POMC)-expressing anorexigenic neurons." (PMID 38541683, 2024). "Granulin, a marker of chronic inflammation associated with insulin resistance, obesity, and type 2 diabetes mellitus, and its expression profile in the POMC secretome also obeyed the regulatory constraint imposed by a gatekeeper function of SIK2." (PMID 39329749, 2024). "Conversely, the deletion of Azgp1 in POMC neurons increased susceptibility to obesity and aggravated metabolic dysfunction." (PMID 38643150, 2024).
Obesity (continued). "POMC or MC4R deletion causes a severe metabolic phenotype characterized by severe obesity and hyperphagia in humans and mice, and MC4R haploinsufficiency in humans is the most common monogenic cause of obesity accounting for up to 5% of cases." (PMID 38992428, 2024). "Future studies should broaden their scope to include a wider array of genes, such as MC4R, LEP, and POMC, to provide a more comprehensive understanding of the combined association between these genes and breastfeeding and their association with obesity." (PMID 39389470, 2024). "This study explored how variations in key genes related to obesity—FOXO3A (forkhead box O3), AMPK (protein kinase AMP-activated), and POMC (proopiomelanocortin)—are associated with extreme obesity (EOB)." (PMID 39484290, 2024). "Patients with HyOb have classically been described as hyperphagic, and this is supported by the phenotype demonstrated in the majority of the monogenic obesity syndromes involving mutations of genes participating in the leptin/POMC/CART/MCR signaling pathway." (PMID 38019584, 2024). "Heterozygosity for a POMC mutation had subtle effects on the expression and function of POMC, which displayed susceptibility to obesity in a large family of Turkish origin." (PMID 39765543, 2024). "A deficiency in the POMC gene and decreased POMC expression are associated with increased food intake, ultimately leading to severe obesity." (PMID 39335335, 2024). "In single-arm, open-label, multicenter, phase 3 trials, subcutaneous once-daily setmelanotide was evaluated for efficacy and safety in individuals with severe obesity due to either POMC deficiency or LEPR deficiency." (PMID 37937009, 2023). "The absence of leptin receptors from POMC neurons induces obesity associated with decreased POMC mRNA, and POMC deficiency in humans is characterized by early-onset obesity." (PMID 37064917, 2023). "In diet-induced obesity, POMC neurons exhibit ER stress, loss of mitochondria/ER contact sites, altered mitochondrial cristae morphology, and a switch toward mitochondrial fission." (PMID 38016943, 2023). "Deletion of leptin receptors on POMC neurons caused mice to be mildly obese and hyperleptinemic while deletion of leptin receptors in AgRP neurons caused hyperphagia, obesity, hyperglycemia and insulin resistance." (PMID 37582711, 2023). "Highly infrequent single gene mutations (such as LEP, LEPR and POMC) stand for rare cases of monogenic obesity; however, some of them are also related to polygenic obesity (such as MC4R and FTO)." (PMID 36980866, 2023). "Leptin analogs and MC4R agonists are exclusively used for patients with obesity secondary to congenital/acquired generalized lipodystrophy and POMC deficiency, respectively." (PMID 37937009, 2023). "Upon the importance of POMC derivatives, the deficiency of functional POMC and derivatives leads to hyperphagia, obesity, hypopigmentation, and adrenal insufficiency." (PMID 37152279, 2023). "Polymorphisms in the POMC gene have previously been associated with longissimus dorsi muscle area and backfat thickness in cattle and with obesity and body mass index in humans." (PMID 38062367, 2023). "Several studies have shown that the inactivation of the melanocortin system or POMC deficiency in animal and human models results in obesity and insulin resistance." (PMID 36986097, 2023). "Consistent with the published data from rodents and humans, chronic loss of function of POMC or MC4R neurons results in massive obesity." (PMID 37069175, 2023). "Inhibition of ERK1/2 blocks the appetite-inhibiting actions of leptin, and deletion of SHP-2 in POMC neurons causes mild obesity, along with an imbalance of energy homeostasis." (PMID 36674935, 2023). "Compelling genetic studies conducted in both rodents and humans have demonstrated that POMC or MC4R loss of function causes obesity and is associated with increased feeding and reduced energy expenditure." (PMID 37069175, 2023).